IL10 (interleukin 10)
Diseases named in the same sentence as IL10 in open-access papers (continued):
Sharing a sentence is not in itself a finding about the gene and the disease.
tumor (continued). "Tregs secrete transforming growth factor-beta (TGF-β) and interleukin-10 (IL-10), which down-regulate antitumour immunity, suppressing the antigen presentation by DCs, CD4+ T helper (Th) cell function and the generation of tumour specific CD8+ cytotoxic T lymphocytes (CTLs)." (PMID 23320561, 2013). "Several pre-clinical cancer models suggest that IL-10 acts as a negative mediator of anti-tumor immunity." (PMID 23755052, 2013). "Research has showed that increased serum IL-10 levels could facilitate development of tumors by suppressing the expression of MHC class I and II antigens and preventing tumor antigen presentation to CD8-cytotic T lymphocytes." (PMID 23460834, 2013). "High levels of IL-6 and IL-10 are observed in HCC patients, correlate with tumor size, and may be helpful to identify a subset of HCC patients with low AFP level." (PMID 27335826, 2013). "Finally, Tregs can secrete two of the main immuno-suppressive cytokines: IL-10 and TGF-β that blunt anti-tumor effector cells such as CD4+, CD8+, and NK." (PMID 24339825, 2013). "The analysis on the T-cell tumor infiltrates showed an increase of CD4+granzyme+ T-cells and a decreased number of CD4+CD25+Foxp3+ Treg elements from mice treated with either gp10025-33 peptide-pulsed DC vaccination or anti-IL-10 mAb administration." (PMID 23663506, 2013). "The release of immunosuppressive factors such as IL-10, TGF-β, and indoleamine 2,3-dioxygense (IDO) by tumor targets has also been reported, which can suppress the adaptive anti-tumor immune response or skew the immune response toward a Th2 response with significantly less anti-tumor capacity." (PMID 24324471, 2013). "Compared with the control group, both treated groups showed significantly higher levels of IL-12 and IFN-γ, but significantly lower levels of immunosuppressive mediators IL-10 and TGF-β1 on day 5 post-treatment, a representative time-point for Tregs depletion and tumor growth inhibition." (PMID 24304581, 2013). "Previously, it was shown that PSK can suppress production of IL-10, VEGF, and TGF-β1, thus, DC/tumor activated with combined OK-432 and PSK may be stimulatory immunogenic due to decreased production of immune-suppressive molecules." (PMID 23555011, 2013). "Another study analyzed the interaction of MDSC with macrophages in a mouse cancer model and showed that, through IL-10 secretion, MDSC induced a type-2 polarization of macrophages which is characterized by a decrease of IL-12 secretion and that promotes tumor growth." (PMID 22822406, 2012). "Moreover, HRS cells have been shown to produce immunosuppressive cytokines, including IL-10, IL-13, and TGF-β and to allow tumor immune escape by several mechanisms." (PMID 22319542, 2012). "The immune cells from pulchellin-treated mice also produced statistically higher concentrations of TNF-α by PEC cells, and IL-4, IFN-γ and IL-10 by splenocytes, and lower concentrations of IL-6 (PEC cells) and TGF-β (splenocytes), than the cells from tumor control mice." (PMID 22827934, 2012). "On the other hand, IL-10 overexpression impairs Th1 cytokine production with an absence of specific T cell activation in the tumor microenvironment, thus contributing to cancer development." (PMID 23148667, 2012). "Consequently, inhibition of TGF-β, IL-10, or VEGF signaling improves DC function and enhances the efficacy of tumor vaccines." (PMID 22592077, 2012). "Several tumor-derived factors such as TGF-β, IL-3, IL-6, IL-10, platelet-derived growth factors, and GM-CSF could also induce ROS production by MDSC." (PMID 22822406, 2012). "Activation of MDSCs not only requires tumour-derived factors (e.g., tumour-derived prostaglandin E2 (PGE2)) but also IFN-γ produced by T cells and factors secreted by tumour stromal cells (like IL-1β, IL-4, IL-6, IL-10, IL-13)." (PMID 22778767, 2012).
tumor (continued). "After 72 h of incubation, we observed increased levels of IFN-γ, TNF-α, IL-10, IL-2, and TGF-β1 in the supernatant of RB tumor cell and PBMC cultures incubated with 1 μg/ml of EpCAM×CD3 antibody compared to an incubation with CD3 or EpCAM monoclonal antibodies alone." (PMID 22328825, 2012). "However, despite these vestiges of inflammation, the tumor milieu tends to be immunosuppressive and is often rich in MDSC and TAM that secrete IL-10 and chemokines." (PMID 23056925, 2012). "Immunohistochemical analysis identified IL-10 only in tumor cells and koilocytic cells, but not in tumor-infiltrating lymphocytes, suggesting that IL-10-producing cells are those transformed by HPV." (PMID 22220169, 2012). "In contrast to that, most of the cytokines which are assumed to promote tumor development are anti-inflammatory cytokines, as for example IL-10 or TGF-β, indicating that IL-17A might be important for tumor rejection." (PMID 22855687, 2012). "Taken together, these results indicated that Pam2 lipopeptides induce IL-10 both in vitro and in vivo in a TLR2-dependent manner, which might play a role in suppressing tumor immunity induced by Pam2 lipopeptides." (PMID 21533081, 2011). "It seems that IL-10 is a significant element in the modulation of NKG2D ligand (MICA), decreasing its expression; therefore, this interleukine may prevent the tumor cytotoxicity mediated by the NKG2D/MICA axis." (PMID 24212778, 2011). "IL-10 and TGF-β play an important role in promoting tumor growth." (PMID 21813021, 2011). "IL10, PTGS2, and FASL are known to suppress the immune response and SMAD7 which inhibit TGFβ, and bone morphogenetic protein expression was downregulated which would lead to an environment favoring tumor growth." (PMID 22013484, 2011). "Interestingly, M2 macrophages (derived from direct tumor cell contact and IL4, IL10 and IL13 exposure) drive a Th2 response resulting in increased expression of anti-inflammatory cytokines and down-regulation of pro-inflammatory mediators." (PMID 21629653, 2011). "Moreover, within the tumor microenvironment and as already proven in other cancers, there are many cells and factors that may inhibit T-cell effector function and hinder the success of effective immunotherapy, such as Treg cells and immunosuppressive cytokines such as IL-10 and TGF-β." (PMID 24212964, 2011). "Here, we showed that systemic injection of Pam2 lipopeptides did not induce effective tumor immunity presumably because of the induction of IL-10 and T reg cells." (PMID 21533081, 2011). "Intrahepatic lymphocytes, isolated from non-tumor tissue, were stimulated with peptides overnight and culture supernatants were screened for CXCL-8, CXCL-9, CXCL-10, CCL-5, CCL-2 as well as IL-17 and the anti-inflammatory cytokine IL-10." (PMID 21876747, 2011). "Furthermore, RCC tumours and TILs produced several cytokines, which inhibit CTL function, including IL-8, TGF-β, and IL-10." (PMID 21934683, 2011). "In tumor-bearing mice, the expression of IL-10 and TGF-β levels were significantly higher than those of normal mice (P < 0.01), whereas the expression of IL-12 was remarkably lower than that of normal mice (P < 0.01)." (PMID 21963624, 2011). "IL10 and IFNγ were chosen as these are not produced by the tumor cell line and their presence denotes expression by immune or other urothelial cells." (PMID 22013484, 2011). "Molecules present in the tumor milieu such as vascular endothelial growth factor (VEGF), interleukin (IL)-10 and prostaglandin-2 (PGE-2) can profoundly affect the biology of DCs making them immunosuppressive, incapable of inducing specific immune responses or capable of inducing regulatory T cells." (PMID 21645356, 2011). "A strongly positive correlation between IL-10 mRNA expression in TAM and tumor stage was seen." (PMID 21595995, 2011).
tumor (continued). "Another interesting example is the effects of macrophages on tumor development, which mainly depends on whether they secrete anti-tumor factors IL-12 and TNF-α, or pro-tumor factors IL-10, VEGF, PDGF, CXCL8, MMP-9 and TGF-β." (PMID 21760911, 2011). "The tumor-infiltrating T cells produce high levels of type 2 cytokines, in particular IL-13 (but not IL-10)." (PMID 21281484, 2011). "This lack of association may be explained by the fact that the methodology used here can detect IL-10 mRNA from both infiltrating immune cells and the BCC tumor cells." (PMID 21980389, 2011). "In vitro stimulated tumor cells seem to differentially influence the phenotype of tumor infiltrating lymphocytes (TILs) so that TILs produced elevated levels of IFN-gamma and reduced levels of IL-10, thus favorably affecting the intratumoral cytokine balance." (PMID 22110526, 2011). "Whereas, tumor-infiltrating in non-treated animals predominantly produced IL-10, the tumor-infiltrating macrophages of antibody treated mice produced IL-12." (PMID 22176642, 2011). "Interestingly, the levels of IL-10 and TGF-β, which are expressed by MHC class IIlow TAMs in the TS/A tumor model, are low." (PMID 21813021, 2011). "They did not proliferate in response to IL-10 either, indicating that in our model, IL-10 does not act as a mitogen to tumor cells." (PMID 20525400, 2010). "One possible explanation for this observation might be the expression of tumour-derived factors, such as VEGF, TGF-β, and IL-10, which have been shown to inhibit differentiation or functional maturation of DCs." (PMID 20969772, 2010). "IL-10 secretion was examined by ELISA but not detected in serum samples from five line 127 tumour bearing mice or five NSC serum samples (all samples showing no IL-10 compared to a positive standard curve, thus there is no graphical data to show)." (PMID 20161707, 2010). "Approximately 2 fold increase in the number of double positive CD8 Perforin+ E7+ T cells was observed in the IL-10R neutralized mice compared to controls, indicating that absence of IL-10 signaling enhances tumor infiltration by potentially cytotoxic T cells." (PMID 20525400, 2010). "Blocking of IL-10 signaling, via neutralization with antibody or due to gene knockout, led to a significant increase in CD11b+ tumor infiltrating cells, which did not reflect a significant increase in numbers of TAM or CD11b+Gr1+ cells." (PMID 20525400, 2010). "TC-1 tumor cells do not express or respond to IL-10, but recruit leukocytes which, within the tumor environment, produce this cytokine." (PMID 20525400, 2010). "In TMV-treated Treg, increased expression levels of phospho-STAT3 and phospho-SMAD2/3 and of IL-10 and TGF-β1 expression as well as production may be responsible for attenuating anti-tumor immune responses in cancer patients." (PMID 20661468, 2010). "Under certain conditions, typically following exposure to IL-10 or TGF-β, dendritic cells within the tumor microenvironment and cancer cells can initiate the development of Tregs limiting effector responses by inhibition of cytotoxic T-cells thus impairing anti tumor immunity." (PMID 20205946, 2010). "On the one hand, increased serum IL-10 levels could facilitate development of cancer by suppressing expression of MHC class I and II antigens and preventting tumor antigen presentation to CD8-cytotoxic T lymphocytes." (PMID 20553628, 2010). "Tumor progression also provoked alterations that changed the peritoneal macrophage profile: at the outset of the neoplastic process, BTM peritoneal macrophages demonstrated consistent TNF-α production and moderate IFN-γ and IL-10 production." (PMID 19534779, 2009). "A band corresponding to phosphorylated JAK2 appeared only when monocytes and tumor cells (MCF-7) were co-cultured together but not when either conditioned media or IL-10, were used (respectively)." (PMID 19718269, 2009).
tumor (continued). "However, IL-1β, IL-6, IL-8, IL-10, IL-12, MCP-1 and MIP-1β were more abundant in high-grade tumours than in low-grade tumours." (PMID 17261184, 2007). "For example, tumor cells may actively produce anti-inflammatory cytokines such as TGF-β, IL-10 in order to suppress DC function and promote tolerance." (PMID 17625013, 2007). "IL-1β, IL-6, IL-8, IL-10, IL-12, MCP-1 and MIP-1β were abundant in high-grade tumours." (PMID 17261184, 2007). "In other models the same cytokine cascade may lead to the production of immune suppressing factors (IL-10, TGF-β, and VEGF), resulting in immune suppression and tumor progression." (PMID 18001476, 2007). "Tumour rates of proliferation and apoptosis have a negative correlation with the CMI-associated cytokines TNF-α and IFN-γ while having a positive one with IL-10 (HI associated)." (PMID 16641913, 2006). "This suggests that the expression of IL-10 is confined to the tumour microenvironment and is not secreted." (PMID 16995954, 2006). "In this paper, we have examined the mechanism of IL-10/IL-10 receptor signalling in two distinct human prostate cell lines, a ‘normal’ prostate epithelial cell line, termed NPTX-1532 and highly metastatic PC-3 ML tumour cells." (PMID 12771930, 2003). "To evaluate whether alterations in PB DCs could depend on tumour-related soluble factors, we analysed the levels of VEGF, IL-10 and spermine in the plasma of nine patients compared with an equal number of control subjects." (PMID 14562018, 2003). "The histological grade of the tumour did not correlate with the IL10 expression, nor did CD3 or CD68 expression." (PMID 11870535, 2002). "This suppression is not mediated by IL-10 and disappears following surgical resection of the tumour." (PMID 10737381, 2000). "Other than the well‐known actions of oncogenic proteins E6 and E7, HPV was proven to exert multiple effects on the tumor microenvironment (TME), including an immunosuppressive effect for the reduced expression of MHC‐1 and an increase of immune‐inhibitory agents such as IL‐10 and TGF‐ß." (PMID 40762035, 2026). "They inhibit the proliferation and function of target immune cells and promote tumor immune evasion by secreting negative cytokines such as interleukin‐10 (IL‐10) and IL‐4, or by directly interacting with target immune cells through CTLA‐4 and transforming growth factor‐beta (TGF‐β)." (PMID 41560416, 2026). "In addition, Gene Set Enrichment Analysis (GSEA) revealed the enriched pathways of TGF-β signaling in non-tumor compartments and IL-10 signaling in tumor compartments from DH areas compared to that from DL areas." (PMID 40229283, 2025). "M2 macrophages secrete immunosuppressive and pro-tumorigenic factors, including IL-10, epidermal growth factor (EGF), VEGF, matrix metalloproteinases (MMPs), deoxypyridinoline (DPD), platelet-derived growth factor (PDGF), and TGF-β, thereby facilitating immune suppression and tumor progression." (PMID 40750884, 2025). "This process involves the secretion of inflammatory cytokines (such as IL-4 and IL-10) and vascular endothelial growth factor (VEGF), which activate relevant signaling pathways, such as NF-kB, thereby promoting the formation of blood vessels and the survival of tumor cells." (PMID 40098971, 2025). "Furthermore, if the IFN-γ- or IL-10-selective epitopes were mixed in a vaccine in either model, tumor growth was no different than in the mice receiving the sham vaccine due to the immune suppressive effects of IL-10 secretion." (PMID 40432134, 2025). "Using this platform, we explored γc cytokine–receptor pairings that either do not occur in nature, are rarely studied in anti-tumour properties (such as IL-10, IFNs) or involve receptors not naturally expressed on T cells (for example, IL-20R, IL-22R, GCSFR, EPOR)." (PMID 40804519, 2025).
tumor (continued). "Cytokine analysis of tumor tissues revealed that the combination of Liensinine and immunotherapy significantly elevated levels of pro-inflammatory cytokines, including TNF-α, IL-12, IFN-γ, and granzyme B, while reducing the levels of immunosuppressive cytokines, such as IL-10 and TGF-β." (PMID 40665352, 2025). "Regarding the cytokine profile, notable modulations were observed in the levels of IL-1β, IL-4, IL-6, IL-10, IL-17A, and TNF-α, particularly in the FMT groups, indicating an influence on the local immune response that could contribute to shaping the tumor microenvironment." (PMID 41614846, 2025). "CD36 also demonstrated positive correlations with immune checkpoint molecules, including C10orf54, EDNRB, TLR4, ENTPD1, IL10, and IL2RA, suggesting that it may contribute to immune escape mechanisms by engaging checkpoint pathways in the tumor microenvironment." (PMID 41550652, 2025). "Finally, mice in which tumours did not develop (CANReject and CRSReject) displayed higher levels of the anti‐inflammatory cytokine, IL‐10, in the midbrain, thalamus and striatum compared to mice that developed tumours or those in which tumours regressed." (PMID 40172096, 2025). "However, increasing evidence suggests that IL-10 is not consistently immunosuppressive and does not always promote tumour immune evasion." (PMID 39325360, 2025). "In TME, M2 macrophage facilitated the development and malignancy of tumor cell via releasing IL-10, TGF-β and other anti-inflammatory cytokines, while M1 polarization of macrophage was induced by some clinical chemotherapy drugs to exhibit the anti-tumor effect." (PMID 41145470, 2025). "Tumor cells secrete chemokines such as regulated on activation, normal T cell expressed and secreted (RANTES) and monocyte chemoattractant protein-1 (MCP-1) to recruit macrophages and promote their polarization toward the M2 phenotype, which secretes pro-tumoral mediators including IL-10 and VEGF." (PMID 41590709, 2025). "These NK cells express also IL-10 and TGF-β that could impair their anti-tumor immunity efficiency." (PMID 40211394, 2025). "Within the tumor microenvironment, M2 cytokines, including IL-4, IL-13, and IL-10, are present, and TAMs in various cancer models exhibit an M2 activation profile characterized by increased expression of CD163, MRC-1, C-type lectins, IL-10, and Arg-1, as well as reduced production of IL-12." (PMID 40544275, 2025). "While polysaccharides can enhance anti-tumor immunity through immune activation, the TME harbors immunosuppressive elements—including regulatory T cells (Tregs), MDSCs, TAMs, and cytokines like TGF-β and IL-10 —that inhibit immune cell activity and compromise immunotherapy efficacy." (PMID 41149588, 2025). "Additionally, some B cells in the tumor may develop regulatory properties (Bregs) under the influence of the TME, contributing to immunosuppression through cytokines like IL-10, IL-35, and TGF-β." (PMID 40636453, 2025). "Macrophages also migrate to the tumor site, where tumor cells are responsible for a switch in macrophage phenotype, favoring a pro-invasive and immunosuppressive M2 state via the release of immunosuppressive factors, such as CSF-1, CCL2, IL-4, IL-6, IL-10, and TGF-β." (PMID 41373591, 2025). "Furthermore, while many γδT cells exert potent anti-tumor effects through the production of pro-inflammatory cytokines like IFN-γ and TNF-α, certain subsets, including IL-10-producing γδT cells, have been identified as immunosuppressive, particularly in solid tumors." (PMID 40226616, 2025). "Additionally, immunosuppressive factors secreted by tumor cells, notably TGF-β and IL-10, may promote DNA damage accumulation and DDR activation by suppressing DNA repair mechanisms." (PMID 40249925, 2025). "Additionally, tumor cells foster an immunosuppressive environment by secreting cytokines with immunosuppressive actions, such as transforming growth factor β (TGF-β) and interleukin-10 (IL-10)." (PMID 40282336, 2025).